INS (insulin)
Diseases named in the same sentence as INS in open-access papers (continued):
Sharing a sentence is not in itself a finding about the gene and the disease.
type 2 diabetes (continued). "Insulin resistance is a key feature of Type 2 Diabetes (T2D), and improving insulin sensitivity is important for disease management." (PMID 35466213, 2022). "The incretins Glucagon-like peptide 1 (GLP-1) and glucose-dependent insulinotropic peptide (GIP), which were suggested to be efficacy in restoring insulin sensitivity, have shown potential in reducing GV in patients with Type 2 Diabetes." (PMID 35968315, 2022). "A previous study reported a similar vasoconstrictor response to insulin in persons with type 2 diabetes." (PMID 34957859, 2022). "In the insulin and type II diabetes signaling pathways in camels, there are about 21 upregulated genes." (PMID 35903143, 2022). "Increased insulin utilization to treat type II diabetes mellitus (DM) can lead to dysfunction of the pancreatic β-cells and their subsequent destruction, which can ultimately lead to a decrease and cessation of insulin production and secretion." (PMID 36128537, 2022). "Studies showed that the majority of patients with type 1 diabetes experienced severe hypoglycemia because of the insulin, and 42.3% and 51.1% of type 2 diabetic patients were due to sulphonylurea (SU) and insulin, respectively." (PMID 36230996, 2022). "We hope that our findings elucidate the molecular mechanism of Sirt3 modulators in regulating insulin signaling pathway and highlight the therapeutic potential of Sirt3 activator in the treatment of type 2 diabetes and metabolic diseases." (PMID 35409099, 2022). "Further, it is known that in the early stage of type 2 diabetes patients have elevated serum insulin levels, most likely as a result of the reduced or lost switch off mechanism." (PMID 35216316, 2022). "The same study showed that persons with type 2 diabetes taking only insulin during Ramadan had a greater incidence (16.8%) of hypoglycemia than those treated with only oral hypoglycemic agents (5.3%)." (PMID 35634376, 2022). "Regarding the glycemic control efficiency of these three basal insulin analogs, a meta-analysis was conducted to compare glargine, detemir, and degludec with respect to their glycemic control in type 1 and type 2 diabetes." (PMID 35890301, 2022). "We report a pediatric case of ketosis-prone type 2 diabetes requiring insulin therapy with four years of follow-up." (PMID 35464505, 2022). "In several studies, ceramide species, i.e., C16:0 and C18:3, in muscle were negatively correlated with insulin sensitivity, while serum C18:0 increased in obese type 2 diabetes subjects compare to their healthy controls." (PMID 35269861, 2022). "John Holloszy’s studies found that exercise improved insulin sensitivity in patients with type 2 diabetes and provided a better understanding of how muscle adapts to endurance exercise." (PMID 36155132, 2022). "Conversion to type 2 diabetes occurs when insulin secretion cannot compensate for insulin resistance in peripheral tissues." (PMID 35050191, 2022). "Retinal microvasculature monitoring using OCTA is vital for patients with type 2 diabetes receiving intensive insulin therapy." (PMID 35459162, 2022). "Metformin, an insulin sensitizer, is the most commonly used first line therapy in type 2 diabetes and has emerged as a potential anti-cancer drug." (PMID 35158824, 2022). "NEW & NOTEWORTHY Glycemic and metabolic improvements are seen in patients with type 2 diabetes after replacing their insulin therapy with DMR and GLP-1." (PMID 34957857, 2022). "Studies revealed that lower OC concentrations were associated with higher risk of type 2 diabetes, metabolic syndrome, high BMI and FBG and low insulin sensitivity." (PMID 35983511, 2022). "Previous human studies have suggested that PGC1α expression and activity is inhibited in obesity and type 2 diabetes, which leads to a disturbance in mitochondrial oxidative capacity and decreased insulin sensitivity." (PMID 36143977, 2022).
type 2 diabetes (continued). "Hyperglycemia in type 2 diabetes occurs when insulin-dependent tissues’ (skeletal muscle, adipose tissue and liver) insulin sensitivity is disrupted, which leads to a significant decrease in their glucose uptake and hyperinsulinemia." (PMID 36678673, 2022). "In Finnish Current Care Guidelines, insulin is typically recommended in Type 2 diabetes (2018) e.g. to control difficult hyperglycemia or if patients show signs of insulin deficiency." (PMID 36033350, 2022). "Due to the progressive nature of type 2 diabetes, insulin therapy often becomes necessary after treatment with oral anti-diabetic drugs (OADs)." (PMID 36104712, 2022). "Type 1 and type 2 diabetes patients are routinely treated with insulin or insulin-releasing drugs in order to reduce their blood glucose levels." (PMID 35203316, 2022). "Previous studies have shown that N1-methylnicotinamide (MNAM) regulates insulin sensitivity and hepatocyte gluconeogenesis in mice with type 2 diabetes by activating SIRT1 and inhibiting the acetylation of FOXO1." (PMID 36295866, 2022). "Subjects with type 2 diabetes presented expected changes in insulin, glucagon and GLP-1 levels after breakfast and a single aerobic exercise session, not accompanied by glycemic variability changes." (PMID 35612843, 2022). "For example, in a Bypass Angioplasty Revascularization Investigation in Type 2 Diabetes (BARI 2D) trial male patients treated with insulin sensitizers had lower episodes of DSPN over 4 years compared to those who received sulfonylurea/insulin." (PMID 36387914, 2022). "We do have access to medications taken at the time of the study visit; however, we did not use this to classify participants as type 1 or type 2 diabetes, as it is possible to be prescribed insulin, the main treatment for type 1 diabetes, for type 2 diabetes." (PMID 36103146, 2022). "In particular, physical exercise enhances circulating levels of BDNF, which are decreased in obesity and type 2 diabetes mellitus, improving lipid oxidation and insulin sensitivity." (PMID 35631195, 2022). "In a separate experimental study, a similar relationship between insulin secretion and melatonin in human type 2 diabetic patients was found: patients with decreased insulin secretion and glucose tolerance had reduced melatonin productions." (PMID 35967633, 2022). "In a study of the KorAHF registry patients with type 2 diabetes, the mortality rate was higher in patients treated with insulin than in patients treated with oral hypoglycemic agents alone." (PMID 36575485, 2022). "A previous study found that a daily injection of 100 mg/kg Schisandra challenges acidic polysaccharides for 8 weeks effectively increased the fasting INS concentrations in rats with type 2 diabetes." (PMID 36148469, 2022). "The use of thiazolidinediones (TZDs) has been for a long time considered as an appropriate treatment for metabolic complications by improving insulin sensitivity in patients with type 2 diabetes." (PMID 36103974, 2022). "A clinical trial on an insulin infusion device, PaQ, was carried out, and the feasibility of its use was confirmed in patients with type 2 diabetes who had been using multiple daily injections (NCT01535612)." (PMID 35890301, 2022). "Type 2 Diabetes (T2D) is a metabolic disorder recognized by decreased insulin sensitivity and elevated blood glucose." (PMID 36358486, 2022). "Previous studies have shown that in patients with type 1 and type 2 diabetes, insulin absorption is significantly faster and postprandial hyperglycemia is significantly reduced after the administration of a needleless jet syringe." (PMID 35574009, 2022). "This study is a post-hoc analysis of a randomized controlled trial (HOME trial) that included 390 patients with advanced type 2 diabetes randomized to 850 mg metformin or placebo up to three times daily concomitant to continued insulin treatment." (PMID 35379238, 2022).
type 2 diabetes (continued). "Treatment of insulin-resistant cells with metformin, a first-line drug used to treat type 2 diabetes, can rescue IR accumulation and the dynamic behavior of these clusters." (PMID 36473871, 2022). "We suggest the use of prandial insulin analogues for patients with type 2 diabetes needing treatment with prandial insulin." (PMID 35288805, 2022). "Exceptions included fasting insulin and hip circumference where the proportion mediated by liability to type 2 diabetes was estimated as 56% and 52%, respectively." (PMID 35129650, 2022). "In patients with type 2 diabetes mellitus (T2D), a decreased gallbladder motility is directly related to reduced BA secretion into the gut and to reduced insulin release." (PMID 36531484, 2022). "Type 2 diabetes mellitus (T2DM) is a metabolic disease characterized by hyperglycemia caused by insulin resistance and deficiency of insulin secretion by the beta cells of the pancreas." (PMID 35842847, 2022). "Thus, dichotomous Non-Alcoholic Fatty Liver Disease - Liver Fat Score (NAFLD-LFS) score defined by the presence of variables such as metabolic syndrome, type 2 diabetes, and biochemical levels of insulin, AST and ALT may be associated with the risk of suffering NAFLD in adulthood." (PMID 36211332, 2022). "These pigs showed diabetic phenotypes such as hepatic insulin resistance and pancreatic cell apoptosis, which modeled type II diabetes better than some pigs with single‐gene modifications." (PMID 35343091, 2022). "In conclusion, glimepiride combined with recombinant human insulin injection has higher application value in the treatment of patients with type 2 diabetes." (PMID 35571731, 2022). "Several traditional medications for the treatment of type 2 diabetes increases the insulin action and its secretion for β-pancreatic cells." (PMID 36313779, 2022). "Currently, low-molecular-weight DPP-IV inhibitors (gliptins) are used in patients with type 2 diabetes based on the observation that DPP-IV inhibition enhances insulin secretion by increasing the bioavailability of incretins." (PMID 35565202, 2022). "Higher protein consumption leads to an increased insulin and insulin‐like growth factor (IGF‐I) concentrations, which promotes adipose tissue deposition and the risk of overweight, obesity, and type 2 diabetes in the subsequent years." (PMID 36200185, 2022). "This is in accordance with a myriad of studies dating back several years that demonstrate that insulin and leptin resistance are important features of obesity, type 2 diabetes, and low-grade inflammation." (PMID 35406000, 2022). "This systematic review and meta-analysis demonstrated the similarity of insulin biosimilar as a treatment for patients with both type 1 and type 2 diabetes." (PMID 35123455, 2022). "Injectable incretin-based therapy plus basal insulin remains a potent and safe therapeutic approach in uncontrolled type 2 diabetes patients previously treated with basal insulin alone." (PMID 36157450, 2022). "Water, glibenclamide and M. dioica extracts were fed to Streptozocin induced type-2 diabetic rat models at a dose of 1.25 g/kg body weight (bw) for 28 days to see what kind of effects they had on serum glucose, insulin, liver glycogen and lipid contents." (PMID 35128091, 2022). "The purpose of this review is to synthesise and discuss the information from the available literature on the relationship between fasting glucose, fasting insulin, and type 2 diabetes (T2D) with migraine." (PMID 35627115, 2022). "The rise in insulin and C-peptide levels in the untreated diabetic rats of the PC group is in contrast to type 2 diabetic animals, where elevated blood glucose is followed by increased insulin synthesis and insulin resistance resulting in hyperglycemia." (PMID 35078449, 2022).
type 2 diabetes (continued). "Qualitative evidence has highlighted individual, healthcare professional, and system-level barriers as reasons for delaying the initiation of insulin therapy to improve glycemic control in people with type 2 diabetes." (PMID 36556420, 2022). "The targets for metformin were mainly enriched in FOXO, AMPK, insulin, and PI3K-Akt signaling pathways, whereas those for vildagliptin were enriched in insulin secretion, cAMP, and maturity onset diabetes of the young pathways." (PMID 35129424, 2022). "Type 1 diabetes is a hyperglycemic condition with a defect in insulin, while type 2 diabetes is mainly characterized by increased levels of sugar, mostly due to a defect in receptors." (PMID 35268639, 2022). "Reduced levels of the glucogenic amino acids serine and glycine have repeatedly been reported in Type 2 Diabetes cases as impaired glucose uptake in insulin-resistant cells triggers hepatic gluconeogenesis, consuming these amino acids." (PMID 35773471, 2022). "The type 2 diabetic mouse model was successfully established as supported by impaired glucose tolerance and insulin sensitivity, as well as elevated fasting blood glucose (>11 mM)." (PMID 36292919, 2022). "Herein, we overviewed the role of GIP and GLP-1 in the pathophysiology of type 2 diabetes and systematically reviewed the efficacy and safety of injectable incretin-based therapy added to basal insulin in light of the results of the SURPASS-5 trial." (PMID 36157450, 2022). "In individuals with adult-onset diabetes, presence of t-GADA is associated with the clinical phenotype of T1D and predicts insulin therapy." (PMID 36992730, 2022). "It, therefore, seems logical that the treatment of type 2 diabetes would be improved by switching from standard insulin treatment to a treatment that bio-mimics the normal physiologic insulin signaling process." (PMID 35163806, 2022). "In the treatment of type 2 diabetes (T2D), if insulin therapy is required, a single injection of basal insulin is usually used initially, but full insulin therapy is often ultimately required." (PMID 35324747, 2022). "It is well known that pioglitazone as a PPARγ agonist can enhance insulin sensitivity for type 2 diabetes but adversely affects body composition and bone metabolism." (PMID 36547073, 2022). "On the other hand, UCP2 overexpression decreases insulin secretion in beta-cells, leading to obesity, β-cell dysfunction, and type 2 diabetes." (PMID 35323702, 2022). "In fact, multiple loci associated with BW at genome-wide significance levels are also inversely genetically correlated with traits such as type 2 diabetes, fasting glucose and fasting insulin during later life." (PMID 35951032, 2022). "One previous study described the automated insulin delivery approach in end stage renal disease, showing promising evidence of safety and efficacy in patients with type 2 diabetes receiving hemodialysis." (PMID 35353250, 2022). "In conclusion, our results demonstrate that a novel HIIT-protocol combining rowing and cycling efficiently improves insulin sensitivity, VO2max, and body composition with preserved responses in sedentary men with obesity and type 2 diabetes." (PMID 36387850, 2022). "Several PTPs, such as PTPN1, PTPN2, PTPN9, PTPN11, PTPRS, and DUSP9, disrupt insulin signaling and trigger type 2 diabetes, indicating that PTPs are promising drug targets for the treatment or prevention of type 2 diabetes." (PMID 35204821, 2022). "Individuals with NODAP have worse glycaemic control, increased need for insulin therapy, higher incidence of pancreatic cancer, and higher hospitalisations and mortality than individuals with type 2 diabetes." (PMID 35406092, 2022). "Insulin–insulin receptor interaction clearly represents the tip of the iceberg in type II diabetes to regulate glucose levels." (PMID 36499769, 2022).
type 2 diabetes (continued). "Several works have demonstrated that in people with type 2 diabetes (T2D), the mechanisms that control the incretin effect are defective, leading to impaired regulation of insulin and glucagon secretion and exaggerated plasma glucose excursions after meals." (PMID 36230573, 2022). "Type 2 diabetes (T2D), characterized by hyperglycaemia, impairment of insulin secretion and insulin resistance, is a global health crisis with ever-growing incidence and prevalence." (PMID 35750681, 2022). "Type 2 diabetes is a metabolic disease that presents with numerous alterations in hormone levels, including increased insulin and cortisol levels, and reduced free triiodothyronine (fT3) and testosterone levels." (PMID 35273609, 2022). "Data on patients with type 1 and type 2 diabetes prescribed insulin in Hong Kong public hospital outpatient clinics from 1 January to 31 December 2009." (PMID 36329678, 2022). "A total of 8 studies reported the treatment of insulin in patients with type 2 diabetes, with 1672 participants (84% of all)." (PMID 36213198, 2022). "Of the study participants, 85.5% had type 2 diabetes, 51% were on oral ant-diabetic treatment while 30.7% were on insulin therapy." (PMID 36443739, 2022). "Persons with LADA who display signs of high autoimmunity lose their residual insulin secretion more rapidly than those with phenotypic Type 2 diabetes, and consequently become earlier insulin-dependent." (PMID 35923626, 2022). "In this report, we presented a case of GCK‐MODY who was initially treated as type 2 diabetes with insulin in pregnancy until a diagnosis of GCK‐MODY was made in the early third trimester." (PMID 36483860, 2022). "Whilst people with type 2 diabetes are treated pharmacologically with metformin, sulfonylureas and ultimately, insulin, nutritional and aerobic exercise interventions have proven highly effective at reducing hyperglycaemia." (PMID 35930075, 2022). "This study aimed to see the circadian propensity of hypoglycemia and its recovery time based on clinical parameters in type 2 diabetes patients on insulin therapy." (PMID 35178205, 2022). "The exceptions were fasting insulin and hip circumference, where the effects indicated partial mediation by liability to type 2 diabetes." (PMID 35129650, 2022). "Multiple studies reported that polyphenols, such as tea polyphenols and grape polyphenols, modulate blood glucose and alleviate type II diabetes by facilitating glucose uptake or improving insulin sensitivity." (PMID 36111501, 2022). "Type 2 diabetes (DM) is a metabolic disease characterized by high blood-glucose levels secondary to an inappropriate insulin secretion for peripheral insulin sensitivity." (PMID 36121152, 2022). "Treatment of obesity and type 2 diabetes with insulin-sensitizers such as TZDs has become a major challenge in clinical practice because of their side effects that include weight gain, cardiovascular complications, and increased risk of fractures." (PMID 36103974, 2022). "Prediabetes is an intermediate stage in the development of type 2 diabetes and is characterized by abnormal high fasting glucose, impaired glucose tolerance, and/or high-fasting insulin." (PMID 35323474, 2022). "Systemic administration of PPARγ agonists thiazolidinediones (TZDs) in type 2 diabetes improves glucose homeostasis in human and animal models through improved insulin sensitivity." (PMID 36568082, 2022). "Insulin sensitizers that were used in treating type 2 diabetes also showed positive effects for curing AD." (PMID 36547082, 2022). "In a non-randomized intervention study, we examined the effect of a novel HIIT-protocol, recruiting both lower and upper body muscles, on insulin sensitivity, measures of metabolic health and adherence in obesity and type 2 diabetes." (PMID 36387850, 2022).